FBXO34 (F-box protein 34)
Description:
Substrate-recognition component of the SCF (SKP1-CUL1-F-box protein)-type E3 ubiquitin ligase complex promoting ubiquitination and proteasomal degradation of specific target proteins including HNRNPU. Regulates both the G2/M transition and anaphase entry in meiotic oocytes (By similarity). (Microbial infection) Plays a positive role in latent HIV-1 activation. Mechanistically, promotes hnRNP U/HNRNPU ubiquitination, which leads to its degradation and abolishment of the interaction between hnRNP U and HIV-1 Rev mRNA.
Synonyms: FBX34; FLJ20725; CGI-301
Tractability: PROTAC: ubiquitination databases record sites on it.
Gene: Protein-coding gene on chromosome 14 (55,271,344 to 55,370,053, forward strand). Ensembl gene ENSG00000178974.
Subcellular location (Human Protein Atlas): Nuclear speckles; Cytosol
Gene Ontology:
Molecular function: protein binding
Biological process: SCF-dependent proteasomal ubiquitin-dependent protein catabolic process
Cellular component: SCF ubiquitin ligase complex
Genetic constraint (gnomAD): Loss-of-function variants: 13 observed, 27.25 expected, observed/expected ratio (o/e) 0.48, 90% interval 0.31 to 0.76. The upper end of that interval is the gene's LOEUF score, 0.76, which puts it in group 3 of 6, group 1 being the genes least tolerant of losing a copy. Missense variants: 823 observed, 900.28 expected, observed/expected ratio (o/e) 0.91, 90% interval 0.86 to 0.97. Synonymous variants: 319 observed, 331.17 expected, observed/expected ratio (o/e) 0.96, 90% interval 0.88 to 1.06.
Homologues: Orthologues: chimpanzee FBXO34 (99% identical), macaque FBXO34 (97% identical), dog FBXO34 (86% identical), pig FBXO34 (85% identical), guinea pig FBXO34 (75% identical), mouse Fbxo34 (71% identical), rat Fbxo34 (71% identical), rabbit FBXO34 (70% identical), tropical clawed frog fbxo34 (49% identical), zebrafish fbxo34 (37% identical). Paralogues in human: FBXO46 (28% identical).
Diseases named in the same sentence as FBXO34 in open-access papers:
FBXO34 is named in the same sentence as 6 diseases in open-access papers, as found by Europe PMC text mining. Sharing a sentence is not in itself a finding about the gene and the disease. The quoted sentences say what the papers report.
COVID-19 (1 paper, 2022). A disease caused by infection with severe acute respiratory syndrome coronavirus 2. "This included FBXO34, CNTN2, and TMCC2 previously linked with COVID-19 severity using association studies." (PMID 36143338, 2022). "Our results included SNPs in the genes FBXO34, Contactin 2 (CNTN2), and Transmembrane And Coiled-Coil Domain Family 2 (TMCC2) which have been previously linked with COVID-19 severity." (PMID 36143338, 2022).
cancer (1 paper, 2022). A tumor composed of atypical neoplastic, often pleomorphic cells that invade other tissues. "A t(12:14) translocation at the 4th month formed Rad51b-Fbxo34 fusion; Ccnd3 regulates G1/S transition and is frequently dysregulated in many cancer types." (PMID 35869059, 2022).
cardiovascular disease (1 paper, 2022). "Moreover, using GWAS, FBXO34 has also been linked with plasma protein levels in cardiovascular disease risk among Europeans, as well as with blood cell count." (PMID 36143338, 2022).
tumor (1 paper, 2021). "It was worth mentioning that FBXO family members FBXO8, FBXO13, and FBXO34 were linked to tumor staging, and FBXO50 had an associated trend with tumor staging." (PMID 35046938, 2021).
FBXO34 also shares sentences with these, for which no sentence is quoted: Airway obstruction (1 paper); emphysema (1).